MDM2 (MDM2 proto-oncogene)
Diseases named in the same sentence as MDM2 in open-access papers (continued):
Sharing a sentence is not in itself a finding about the gene and the disease.
cancer (continued). "Cancer cells with AKT pathway activation are sensitive to MDM2 antagonists, confirming the importance of MDM2 for cell survival." (PMID 24349524, 2013). "We report here that in human cancer cell lines that over-express MDM2, we detect high expression of the mdm2-C transcript and MDM2-C protein." (PMID 24147044, 2013). "Many human cancer cell lines over-express MDM2 protein and have been used for previous MDM2 studies." (PMID 24147044, 2013). "MDM2 over-expression in cancers is often accompanied with the over-expression of alternatively spliced mdm2 transcripts." (PMID 24147044, 2013). "Using this MDM2 antibody we observed high basal levels of endogenous MDM2-C protein in various MDM2 over-expressing cancer cell lines and tissues." (PMID 24147044, 2013). "Overexpression of the E3 ubiquitin ligase MDM2 is one of the only cellular mechanisms for degradation of Rb in cancer cells that has been characterized to date, but the factors driving MDM2 overexpression in cancer systems remain obscure." (PMID 23894550, 2013). "Two major cancer related proteins that functionally interact with MDM2 and are involved in cell proliferation and cell cycle control, are E2F and RB." (PMID 24147044, 2013). "Our results showed that U87MG cells acquired resistance to 5-FU through its conversion to cancer stem cells along with upregulation of mdm2 oncogene and ABC transporter genes, ABCB1 and ABCG1." (PMID 24391839, 2013). "All three types of cancer display distinct genomic aberration patterns in 12q14-15 region in spite of having MDM2/CDK4 co-amplification." (PMID 24261984, 2013).
cancer (continued). "High expression of MDM2 has been detected in several cancers and is related to decreased response to treatment and poor prognosis." (PMID 24340057, 2013). "Together, these data suggest that rapamycin suppresses MDM2 protein expression, resulting in sensitization of cancer cells to doxorubicin-induced cell death." (PMID 23638184, 2013). "Alternatively spliced mdm2 transcripts are expressed in many forms of human cancer and when they are exogenously expressed they transform human cells." (PMID 24147044, 2013). "Various MDM2 inhibitors, including antisense oligonucleotides, synthetic small molecules, and natural products, have shown anti-cancer activity in vitro and in vivo." (PMID 22911819, 2012). "A structure-based rational drug design strategy including SAR-by-NMR screening was successfully applied in developing potent anti-cancer agents based upon inhibitory activity of mdm2." (PMID 22748190, 2012). "Over-expression of MDM2 has been detected in some malignancies; therefore, MDM2 targeting via utilization of antagonists has been indicated as a potential approach to anti-cancer therapy." (PMID 22844496, 2012). "The answers to these questions will be important for understanding the importance of the Mdm2-MdmX heterodimer in tumorigenesis and for determining the feasibility of the Mdm2-MdmX heterodimer as a target for cancer therapy." (PMID 22410433, 2012). "The MDM2 oncogene is overexpressed in various human cancers and its expression correlates with the phenotypes of high-grade, late-stage, and resistant tumors." (PMID 23244604, 2012). "Most of these regions have been validated to encompass or closely near to cancer related genes such as MDM2, MYC, EGFR, ERBB2, CCND1, ARNT." (PMID 23285074, 2012).
cancer (continued). "Elevated levels of MDM2 protein (expression and/or gene amplification) were observed for several types of cancer." (PMID 23251530, 2012). "Thus, the roles of MDM2 T309G polymorphisms might differ in different cancers." (PMID 22844496, 2012). "As one of the most studied oncogenes, the MDM2 oncogene plays an important role in cancer development, progression, and treatment." (PMID 22911819, 2012). "MDM2 overexpression has been correlated with poor prognosis, increased metastasis and increased aggressiveness of human cancers." (PMID 22911819, 2012). "Four single nucleotide polymorphisms (SNPs) in MDM2 and p14ARF (MDM2-rs2279744, MDM2-rs937283, p14ARF-rs3731217, and p14ARF-rs3088440) were genotyped in 156 patients with SGC and 511 cancer-free controls." (PMID 23145162, 2012). "To further validate the fact that 25-OCH3-PPD targets MDM2 to exert its anti-cancer activities, we compared the effects of 25-OCH3-PPD on parent and MDM2 knockdown (KD) MCF7 inducible cells." (PMID 22911819, 2012). "In this study, we showed that the upstream region of MDM2 is hypermethylated in most cancer samples." (PMID 22133303, 2011). "We also found that, in some cancer samples, hypomethylation occurred along with MDM2 amplification at the same site, suggesting that there is major dysregulation of the MDM2-mediated pathway at both the genetic and epigenetic levels." (PMID 22133303, 2011).
cancer (continued). "Specific Raf, MEK, PI3K, Akt, mTOR and Mdm-2 inhibitors have been developed and represent promising therapies for cancer and other proliferative diseases including premature aging." (PMID 21422497, 2011). "Our analysis suggests that the overexpression of MDM2, observed in many types of cancer, can disrupt the operation of this adaptive mechanism by making it less responsive to the modulating signals after DNA damage occurs." (PMID 21829536, 2011). "Mutations in Mdm2 that disrupt RP binding have been detected in human cancers; however, the physiological significance of the RP-Mdm2 interaction is not completely understood." (PMID 21406728, 2011). "Down-regulation of Rb protein has been reported previously in several cancer cell lines after exposures to an Mdm2 antagonist nutlin-3." (PMID 21629792, 2011). "To date, a number of studies have explored the association between MDM2 SNP309 and the risk of various types of cancer, including brain, breast, colorectal, hepatocellular, lung, ovarian, gastric, uterus, and so on." (PMID 21619694, 2011). "From the time that this well-characterized functional polymorphism was identified, a variety of case-control studies have been published that investigate the possible association between MDM2 SNP309 and cancer risk." (PMID 21619694, 2011). "In this study, we have examined the potential of peptide nucleic acid (PNA) 9-aminoacridine conjugates to modulate the pre-mRNA splicing of the mdm2 human cancer gene in JAR cells." (PMID 20591158, 2010). "Cancer diagnosed in affected carriers with MDM2 GG/GT was on average 9 years earlier than that in affected carriers carrying the TT genotype." (PMID 20520810, 2010).
cancer (continued). "When we adjusted for confounders, the MDM2 SNP309 effect became significant overall and we observed a 58% higher cancer risk in the G allele carriers compared with TT homozygotes." (PMID 20520810, 2010). "This opens new avenues for the development of new anti-cancer drugs or regimens for treating cancer patients, especially those with elevated expression of the Mdm2 oncoprotein." (PMID 21317463, 2010). "Here we describe the interactions we found out in this group between MDM2 SNP309 G/G, BRCA1/2 mutations and clinical findings including cancer onset age, survival, and the presence of other cancers." (PMID 19226467, 2009). "The MDM2 gene has been found to be over-expressed by amplification in several cancers with the highest frequency observed in soft tissue sarcomas." (PMID 20030851, 2009).